GRN (granulin precursor)
Diseases named in the same sentence as GRN in open-access papers (continued):
Sharing a sentence is not in itself a finding about the gene and the disease.
tumor (continued). "Finally, we compared the ability of parental, GRN or EphA2 KO MSTO-211H cells to modulate in vivo tumor formation." (PMID 36471440, 2022). "Endothelial cells that highly expressed ACKR1 and PLVAP could enhance the transmigration of lymphocytes, and GRN was found to promote angiogenesis and tumor cell proliferation." (PMID 34805166, 2021). "Both cisplatin and GRN A were able to inhibit the tumor growth significantly." (PMID 30301274, 2018). "We speculated that GRN, as an upstream gene protein, might indirectly promote angiogenesis and lymphangiogenesis of tumor by regulating the expression pathway of VEGFA." (PMID 24349832, 2013). "The GRN gene (granulin, MIM#138945) encodes an 88-kDa secreted growth factor progranulin, which is involved in multiple physiological functions, including wound healing, tumor growth, and embryonic brain development." (PMID 23342160, 2013). "As a result, we hypothesized that GRN could have a role in tumor immunology." (PMID 37091137, 2023). "Additionally, CTHRC1 overexpression induced tumor associated macrophage infiltration via AnxA1/FPR1 and GRN/TNFRSF1A signaling pathway, indicating CTHRC1 might be a promising predictive factor for immunotherapy." (PMID 37404760, 2023). "Importantly, there are also many reports about the relationship between GRN and tumor biology." (PMID 34002672, 2021). "Finally, GRN has demonstrated effects on the tumor microenvironment." (PMID 26000098, 2015). "Our study identifies GRN as a key regulator of both chemo-resistance and immunotherapy resistance in SCLC, acting through both tumor-intrinsic mechanisms and interactions with the TME." (PMID 39910394, 2025). "Moreover, studies exploring dynamic fluctuations in GRN levels during treatment and its interaction with immune checkpoint pathways and T-cell infiltration are needed to deepen our understanding of GRN’s role in shaping tumor immunogenicity and therapeutic resistance." (PMID 39910394, 2025). "Relative to Post-OP levels, 64 uEV proteins changed significantly at GBM tumour recurrence (p ≤ 0.05), including three proteins (GGH, GRN, ITM2B) that increased by ≥2-fold in the REC group (adjust p-val≤0.05)." (PMID 38212481, 2024). "On the other hand, the communication patterns of the target cells suggested that incoming tumor epithelial cell signalings were dominated by mode 1, which included signaling pathways such as CD99 and MK, as well as PTN, CEACAM, CD96, and GRN." (PMID 38482016, 2024). "On the other hand, pRCC showed upregulation of TFPI2, FSTL1, FAS, and PIGR in the epithelial/tumor, C1QTNF3 and GRN in the endothelial, and ITGAX, HLA-DQA1, IL4I1, and CTSC in the immune compartments." (PMID 38703764, 2024). "Ten signaling pathways only existed in the lymphatic metastases, including CD22, CD45, IL16, SPP1, LIGHT, ANGPTL, GRN, ncWNT, PERIOSTIN, and NEGR, in addition to the classical ncWNT pathways that can promote tumor progression." (PMID 37221625, 2023). "Tumor cells expressed relatively high levels of EGFR, FGFR1, and FGFR2, while their corresponding ligands, such as COPA, GRN, HBEGF, FGF2, FGF7, and FGF18, were widely expressed in fibroblast cells." (PMID 34459128, 2021). "Moreover, we observed AE signal activation, mainly manifested as GRN and GAS signal transmission, reflecting epithelial cell functional differentiation during tumour progression." (PMID 40539065, 2025). "For instance, O. viverrini-Granulin-1 (Ov-GRN-1), which has a similar sequence of mammalian granulin (an important growth factor likely to be involved in carcinogenesis and tumor spreading), was identified in the biliary epithelia of O. viverrini-infected hamsters." (PMID 35326593, 2022). "Important to note, however, is that while GRN stimulates tumor progression, it does not induce malignant transformation on its own." (PMID 34366786, 2021).
tumor (continued). "We identified multiple tumor-immune interactions, for example between CXCR3, CCL5, TNFRSF1B, and VCAM1-expressing malignant T cells and macrophages/fibroblasts positive for CXCL9, CCR1, GRN, and IGTB1, respectively." (PMID 33816243, 2021). "GRN, CD5L, ENO1, CHL1, CRISP3, VASN, and TNIK promote the invasive ability of tumor cells." (PMID 32953262, 2020). "How can we explain that GRN exhibits tumor-promoting functions in other cancers but does not impact on neoplastic capabilities of CLL cells?" (PMID 31200555, 2019). "Moreover, analysis of gene expression data in breast cancer patients revealed a significant correlation between GRN expression and STAT3 gene signatures, increased tumor grade, and reduced patient survival." (PMID 26000098, 2015). "GRN is a potent proliferative agent but has other pro-tumor qualities that are not yet well characterized." (PMID 19816559, 2009). "The role of GRN as a chemo-resistance driver was further confirmed across multiple independent SCLC transcriptomic data from SCLC cell lines, PDX, Circulating Tumor Cells derived xenograft (CDX), and GEMM models, where GRN expression was significantly associated with chemotherapy responses." (PMID 39910394, 2025). "Of note, GRN (protein name, progranulin) and PSAP (prosaposin) displayed significant differential abundance between all three clinical timepoints (Pre-OP, Post-OP and REC) and thus are putative candidate biomarkers of GBM tumour burden, tumour recurrence and treatment resistance." (PMID 38212481, 2024). "In addition, these CENPF-related genes exhibited the expression differences between normal and tumor tissues: the expression of TOP2A or KIF23 was significantly upregulated in LPS, while that of BAG1,PNPLA2, CRYL1 or GRN was significantly downregulated in LPS or MRCLPS compared to normal tissues." (PMID 37108172, 2023). "The interactions where non-tumor cells influenced tumor cells included NAMPT → INSR, MIF → CD74 and CXCR4, GRN → SORT1, and CD99 → CD99." (PMID 39095793, 2024). "However, despite the presence of significantly expressed ligand–receptor pairs in tumor cells, CAF1, and CAF2 cells (e.g., GRN/SORT1, PLA2G2A/a5b1 complex), there is a lack of spatial proximity between CAF1 and CAF2 cells." (PMID 38229179, 2024).
cancer (84 papers, 2006 to 2026). A tumor composed of atypical neoplastic, often pleomorphic cells that invade other tissues. "The GRN protein has been linked to the maintenance of cancer stem cells, the stimulation of cell growth, and the development of metastasis." (PMID 40650152, 2025). "Close monitoring of GRN protein levels will be needed to ensure expression within a physiological range, as elevated GRN levels have been associated with cancer, metabolic disease, and chronic inflammatory states." (PMID 34366786, 2021). "Granulin (GRN) has a critical role in different cancers, and its products cause malignant transformation, induce metastases, and interfere with antiapoptotic processes." (PMID 35186706, 2021). "Progranulin (encoded by the gene GRN), also known as prostate cancer cell-derived growth factor (PCDGF), or granulin/epithelin precursor, is a secreted 88-kDa glycoprotein composed of 7.5 cysteine-rich tandem repeats." (PMID 30454027, 2018). "The homologue of human GRN in O. viverrini (Ov-GRN-1) has been demonstrated to be a potent stimulator of cell proliferation and has been associated with cancer progression." (PMID 27386259, 2016). "We use TCGA data to learn more about the context and causes of GRN expression in cancer." (PMID 37091137, 2023). "GRN overactivity occurs in many types of cancers and imparts an aggressive phenotype on poorly tumorigenic carcinomas." (PMID 40776410, 2025). "In cancer settings, GRN engages PI3K–AKT, MAPK–ERK, and NF-κB pathways, thereby enhancing proliferation and stress resistance." (PMID 41488055, 2025). "In cancer, GRN’s involvement is complex, with evidence suggesting both pro-tumorigenic and anti-tumorigenic effects depending on the specific context." (PMID 38255751, 2024). "Using CIBERSORT and the GEPIA correlation module, we also investigated the link between GRN and immune infiltrates in cancer." (PMID 37091137, 2023). "The bubble map indicated that the receptor TNFRSF1A and its corresponding ligand GRN played an important role in the communication between myofibroblasts and basal cells or cancer stem cells." (PMID 35620271, 2022). "Granulin (GRN), a growth regulatory glycoprotein which promotes cancer progression and which interacts with HS, is differentially expressed as measured by qPCR by 5-fold." (PMID 30651077, 2019). "GRN was demonstrated to have growth factor activity and positively impacted on cancer growth in preclinical solid tumor models." (PMID 31200555, 2019). "Our previous study confirmed that the inhibitory effect of GRN A on cancer cells is associated with the interaction between GRN A and ENO1, and GRN A is capable of inhibiting the function of ENO1." (PMID 30301274, 2018). "Our present study showed that GRN A displays significant inhibition effects on migration and invasion of cancer cells." (PMID 28415822, 2017). "Previous study in our laboratory has shown that GRN A is able to inhibit cancer cell growth significantly." (PMID 28415822, 2017). "More studies are needed to document if GRN A treatment of cancer cells is able to affect the interaction of ENO1 with plasminogen, uPA and uPAR." (PMID 28415822, 2017). "GRN-expressing bone marrow cells induce stromal fibroblasts to express genes involved in inflammation and matrix remodeling, thereby promoting cancer metastasis." (PMID 26000098, 2015). "We found progranulin (GRN), a protein that has been linked to inflammation and cancer, to be upregulated in the serum of CLL patients compared to healthy controls, and increased GRN levels to be associated with an increased hazard for disease progression and death." (PMID 31200555, 2019). "Increased GRN serum or tissue levels, in contrast, were associated with cancer and connected to a negative prognosis, for example in carcinomas of the breast, ovary, liver, prostate, and lung, and in brain tumors like glioblastoma." (PMID 31200555, 2019).
cancer (continued). "Thus, Grn−/− bone marrow chimeric mice are indeed a suitable model to detect a potential effect of GRN on cancer growth." (PMID 31200555, 2019). "In addition to its growth-promoting function, GRN is also an established survival factor in cancer models." (PMID 26000098, 2015). "Proteins such as GDF15, MERTK, MRP2, SMPD-1, GPNMB, GRN, and FSTL1, while less widely recognized, have emerging roles in cancer progression, immune modulation, and metabolic regulation." (PMID 40805206, 2025). "We found that cancer epithelial cells with elevated SHCBP1 expression exhibited a strong interaction with stromal cells through the EGF, VEGF, IGFBP, CypA, GRN, and PTN signaling pathways." (PMID 40799237, 2025). "Excitingly, a recent study demonstrated that GRN promotes temozolomide resistance of GBM cells via modulating DNA damage repair pathways and inducing cancer stemness." (PMID 38212481, 2024). "LA-TAMs also participated in the modification of cancer cells by SPP1, VEGFA, RETN, GRN, ADGRE5, and HBEGF secretion." (PMID 37649596, 2023). "Specifically, M1 and M2 macrophages targeted other cells in the GALECTIN, GRN and SPP1 signaling pathway networks, and GBM cancer cells regulated other cells in the MK and PTN signaling pathway network." (PMID 35558067, 2022). "Notably, EGFR and its receptors, including TGFB1, MIF, HBEGF, GRN, COPA, and AREG, were upregulated in cancer cells and fibroblasts." (PMID 34326696, 2021). "In contrast, overexpression of ENO1 reversed the effect of GRN A on migration of cancer cells; the number of migrated cells was increased to 346 ± 46 in ENO1 transfected cancer cells treated with GRN A, compared with that (144 ± 21) in cells transfected with the control plasmid." (PMID 28415822, 2017).
infection (19 papers, 2007 to 2026). The state of being infected such as from the introduction of a foreign agent such as serum, vaccine, antigenic substance or organism. "GRN-5′AS and GRN-intAS are both expressed in monocytes upon infection, while only GRN-5′AS shows some expression in the brain." (PMID 30610612, 2019).
neurological diseases (16 papers, 2017 to 2025). "GRN mutations cause a range of neurological disorders, presenting an allele dose-dependent pattern." (PMID 36009452, 2022). "Future research needs to further explore the specific mechanism of the GRN gene in nervous system diseases, in order to provide new targets and strategies for the prevention and treatment of related diseases." (PMID 40736401, 2025).
metabolic disease (6 papers, 2015 to 2025). A congenital disorder (due to inherited enzyme abnormality) or acquired (due to failure of a metabolically important organ) disorder resulting from an abnormal metabolic process. "Expression of some of these genes (IL6R, WNK1, GRN) has been previously reported to correlate with metabolic disorders." (PMID 32956382, 2020).
movement disorder (4 papers, 2016 to 2024). Neurological conditions resulting in abnormal voluntary or involuntary movement, which may impact the speed, fluency, quality and ease of movement. "This could be explained by the fact that clinical presentations of GRN mutations also include movement disorders with extrapyramidal features and the sub-process information processing was only composed of tests with a strong motor component, while the sub-process attention was not." (PMID 39500348, 2024). "The evaluation of plasmatic progranulin levels is useful for raising the suspicion of a GRN mutation and should be performed even in the absence of positive family history for movement disorders." (PMID 33467748, 2021).
immune dysfunction (3 papers, 2018 to 2024). "FTD may be associated with chronic immune dysfunction, microglial activation and raised inflammatory markers, particularly in progranulin (GRN) mutation carriers." (PMID 30111356, 2018).
infectious disease (3 papers, 2014 to 2024). A disorder directly resulting from the presence and activity of a microbial, viral, or parasitic agent in humans. "GRN, at elevated levels, has been associated with poor prognosis in infectious diseases." (PMID 38166912, 2024).
autosomal dominant inherited disorder (2 papers, 2014 to 2017). "Moreover, a number of genes have been recognized as causative of autosomal dominant inherited disorder, such as mutations within Microtuble Associated Protein Tau (MAPT) and Granulin (GRN) genes along with repeat expansion of C9orf72 gene." (PMID 25188321, 2014).
Brain Diseases (2 papers, 2018 to 2019). "Neuroprotective effects of PGRN have also been observed in models of other brain disorders, suggesting that PGRN may have beneficial effects in various brain diseases not restricted to FTD with GRN haploinsufficiency." (PMID 30326935, 2018).
genetic diseases (2 papers, 2013 to 2025). "As many FTLD-GRN cases are caused by nonsense mutations, which result in PTCs in the GRN mRNA, another potential treatment strategy may be nonsense suppression therapy, which has been investigated in many other genetic diseases caused by nonsense mutations." (PMID 40713630, 2025).
psychiatric disorder (1 paper, 2016). A disorder characterized by behavioral and/or psychological abnormalities, often accompanied by physical symptoms. "In this view, psychiatric disorders might represent a long lasting preclinical phase preceding FTD in some GRN mutation carriers." (PMID 26869919, 2016). "However, since (i) mutations in GRN cause bvFTD and (ii) GRN knock-out models are characterized by prominent behavioral disturbances, the study of such animal models could be useful to understand the molecular mechanisms underlying psychiatric disorders." (PMID 26869919, 2016).
skeletal disease (1 paper, 2022). "Also, many of these novel putative core cartilage GRN genes have been found to be expressed in OA cartilage, and even to have a role during the progression of this skeletal disease, further supporting the importance of these genes during cartilage development." (PMID 35784462, 2022).
GRN also shares sentences with these, for which no sentence is quoted: Arthritis (17 papers); prostate carcinoma (10); type 2 diabetes (10); colorectal cancer (9); glioblastoma (9); inflammatory bowel disease (9); amyloid (8); cardiovascular diseases (8); kidney disease (7); Hypertension (6); metabolic syndrome (6); semantic dementia (6); Ataxia (5); bacterial infection (5); neuronal ceroid lipofuscinosis type 11 (5); non-small cell lung carcinoma (5); osteoporosis (5); psoriatic arthritis (5); acute kidney injury (4); asthma (4); Batten disease (4); bipolar disorder (4); bladder cancer (4); cervical cancer (4); chronic periodontitis (4); Gliosis (4); influenza (4); invasive ductal carcinoma (4); lymphoma (4); myocardial infarction (4).
A further 192 diseases each share a sentence with GRN in 4 papers or fewer.